MDC1 (mediator of DNA damage checkpoint 1)
Description:
Histone reader protein required for checkpoint-mediated cell cycle arrest in response to DNA damage within both the S phase and G2/M phases of the cell cycle. Specifically recognizes and binds histone H2AX phosphorylated at 'Ser-139', a marker of DNA damage, serving as a scaffold for the recruitment of DNA repair and signal transduction proteins to discrete foci of DNA damage sites. Also required for downstream events subsequent to the recruitment of these proteins. ATM and CHEK2 may also be activated independently by a parallel pathway mediated by TP53BP1. Required for chromosomal stability during mitosis by promoting recruitment of TOPBP1 to DNA double strand breaks (DSBs): TOPBP1 forms filamentous assemblies that bridge MDC1 and tether broken chromosomes during mitosis. Required for the repair of DSBs via homologous recombination by promoting recruitment of NBN component of the MRN complex to DSBs.
Synonyms: KIAA0170; NFBD1; Em:AB023051.5
Tractability: Small molecule: it has a high-quality binding pocket. PROTAC: UniProt records ubiquitination sites on it; ubiquitination databases record sites on it; its protein half-life has been measured.
Gene: Protein-coding gene on chromosome 6 (30,699,807 to 30,717,562, reverse strand). Ensembl gene ENSG00000137337.
Subcellular location: Nucleus; Chromosome
Subcellular location (Human Protein Atlas): Nuclear bodies; Nucleoplasm
Pathways (Reactome):
DNA Repair: Nonhomologous End-Joining (NHEJ); Processing of DNA double-strand break ends; Recruitment and ATM-mediated phosphorylation of repair and signaling proteins at DNA double strand breaks
Cell Cycle: G2/M DNA damage checkpoint
Metabolism of proteins: SUMOylation of DNA damage response and repair proteins
Gene Ontology:
Molecular function: chromatin-protein adaptor activity; histone reader activity; protein binding
Biological process: DNA damage response; DNA replication checkpoint signaling; protein localization to site of double-strand break; mitotic intra-S DNA damage checkpoint signaling; chromatin organization
Cellular component: chromosome; nuclear body; nucleoplasm; nucleus; site of double-strand break
Genetic constraint (gnomAD): Loss-of-function variants: 82 observed, 152.05 expected, observed/expected ratio (o/e) 0.54, 90% interval 0.45 to 0.65. The synonymous counts are far from expectation, so gnomAD's model fits this gene poorly and the ratio says little. Missense variants: 2,119 observed, 2,616.9 expected, observed/expected ratio (o/e) 0.81, 90% interval 0.78 to 0.84. Synonymous variants: 797 observed, 989.39 expected, observed/expected ratio (o/e) 0.81, 90% interval 0.76 to 0.85.
Homologues: Orthologues: chimpanzee MDC1 (98% identical), macaque MDC1 (91% identical), pig MDC1 (63% identical), dog MDC1 (62% identical), mouse Mdc1 (48% identical), rat Mdc1 (43% identical), tropical clawed frog mdc1 (23% identical), zebrafish mdc1 (16% identical), Caenorhabditis elegans picd-1 (11% identical). Paralogues in human: PAXIP1 (10% identical).
Diseases named in the same sentence as MDC1 in open-access papers:
MDC1 is named in the same sentence as 67 diseases in open-access papers, as found by Europe PMC text mining. Sharing a sentence is not in itself a finding about the gene and the disease. The quoted sentences say what the papers report.
breast carcinoma (12 papers, 2010 to 2026). "DDR gene mutations correlated with poor prognosis in breast cancer (BC) patients, and those who harbored the MDC1 gene mutation had the worse prognosis." (PMID 36816926, 2023). "Nandrolone phenpropionate, which is used to treat, among others, breast carcinoma, was further associated with the MDC1 protein (mediator of DNA-damage checkpoint 1)." (PMID 27025271, 2016). "Six paired breast cancer tissues and adjacent normal tissues to verify the protein expression level of MDC1, PSMB1 and PSMD14 via immunohistochemical staining." (PMID 37350936, 2023). "LRH1 promotes the chemoresistance of breast cancer cells by enhancing the expression of MDC1 and attenuating DNA damage." (PMID 33194722, 2020). "After 8 cycles of NAC, women whose breast cancers showed a PPR also had significantly lower levels of expression of mDC1 CD40 (p = 0.001) and CD86 (p = 0.001), compared with HFDs." (PMID 28913366, 2017). "MDC1 was found to be expressed lowly in various cancers including lung cancer, breast carcinomas and gastric carcinoma." (PMID 25198518, 2014). "MDC-1 has been identified as a prognostic marker for recurrence of early stage breast cancer and its level is positively correlated with recurrence in breast cancer." (PMID 32784600, 2020). "A Caucasian study reported no variant of MDC1 was associated with breast cancer risk as well as DNA-damaging effects of radiation therapy." (PMID 25198518, 2014). "Interestingly, MDC1 deficiency also causes PARPi resistance in the context of BRCA1 deficiency as demonstrated using the human retinal pigment epithelium RPE-1 cells and mouse mammary tumor-derived KB1P-G3 cells." (PMID 41408464, 2026). "Elegantly reinforcing the molecular relevance of MDC1-PHB to the activity of GPR19, we found that this cohort of in silico-derived proteins interacts with each other to create a network of interconnected signaling functions linked to breast cancer, aging, and DDR." (PMID 37239845, 2023). "Subsequently, we explored the protein levels of MDC1, PARP3, PSMB1, PSMB9, PSMD2, PSMD7, and PSMD14 in normal breast tissues and breast cancer tissues." (PMID 37350936, 2023). "We found that the expression of MDC1, PSMB1 and PSMD14 were concurrently upregulated in breast cancer samples, suggesting the potential of the prognostic model." (PMID 37350936, 2023). "Consistent with the Immunohistochemistry (IHC) results, the expression of MDC1, PSMB1, PSMD2, PSMD7 and PSMD14 were significant augmented in breast cancer patients (P < 0.05)." (PMID 37350936, 2023). "The protein levels of MDC1, PSMB1, PSMB9, PSMD2, PSMD7, and PSMD14 were increased, while that of PARP3 was decreased in breast cancer tissues compared with normal tissues." (PMID 37350936, 2023). "We analyzed a prognostic model based on seven DDR genes, PSMD2, PSMD7, PSMD14, PARP3, MDC1, PSMB1, and PSMB9, reflecting an enhanced level of predicting the survival and prognosis of patients with breast cancer." (PMID 37350936, 2023). "Furthermore, we investigated the function of the five highly expressed genes (MDC1, PSMB1, PSMD2, PSMD7, and PSMD14) in breast cancer MDA-MB-231 cells to test the prognostic model." (PMID 37350936, 2023).
breast carcinoma (continued). "In addition, we investigated the roles of MDC1, PSMB1, PSMD2, PSMD7, and PSMD14 in the invasion and metastasis of breast cancer." (PMID 37350936, 2023). "We established a seven-gene prognostic model comprising MDC1, PARP3, PSMB1, PSMB9, PSMD2, PSMD7, and PSMD14 genes, which provides a basis for further exploration of a population-based prediction of prognosis and immunotherapy response in patients with breast cancer." (PMID 37350936, 2023).
lung carcinoma (8 papers, 2013 to 2022). "The gene-based analysis rested with these SNPs suggested the MDC1 as a susceptible gene for lung cancer (P = 0.009)." (PMID 25198518, 2014). "In conclusion, our data showed that the promoter SNP rs4713354A>C of MDC1 and the MDC1 gene were associated with lung cancer risk in Chinese by influencing MDC1 expression." (PMID 25198518, 2014). "Further analysis supported the MDC1 gene to be a susceptible gene and rs4713354A>C to be a susceptible loci of lung cancer." (PMID 25198518, 2014). "Further analysis based on the results from the five putatively functional SNPs of MDC1 suggested MDC1 to be a susceptible gene for lung cancer." (PMID 25198518, 2014). "In the current study, based on a two-stage case-control study with a relatively large sample size, we showed that a promoter SNP of MDC1 contributed to a significant increased risk of lung cancer in Chinese." (PMID 25198518, 2014). "Here, we found that the SNP rs4713354A>C of MDC1 was associated with risk of lung cancer in Chinese." (PMID 25198518, 2014). "In a two-stage case-control study, we tested the association between 5 putatively functional SNPs of MDC1 and lung cancer risk in a southern Chinese population, and validated the promising association in an eastern Chinese population." (PMID 25198518, 2014). "Our data suggested that the SNP rs4713354A>C of MDC1 may be a functional genetic biomarker for susceptibility to lung cancer in Chinese." (PMID 25198518, 2014). "Moreover, the toxin cantharidin can cause DNA damage by inhibiting MDC1 expression in lung cancer cells." (PMID 25198518, 2014). "The rs4713354C variant genotypes could cause a low expression of MDC1 in vivo and thus contributed to an increased lung cancer risk." (PMID 25198518, 2014). "The gene-based association analysis further revealed that the MDC1 gene to be associated with lung cancer risk with an approaching statistical significance (P = 0.057) based on the results from above five SNPs, and the most significant associated-SNP was rs4713354A>C (P = 0.003)." (PMID 25198518, 2014). "In the current study, we tested the hypothesis that these putatively functional SNPs of MDC1 were associated with risk of lung cancer based on a two-stage case-control study, and assessed the function of promising SNPs by bioinformatics analysis." (PMID 25198518, 2014). "Distribution of genotypes of MDC1 and associations with the risk of lung cancer." (PMID 25198518, 2014). "Both the SNP rs4713354A>C and MDC1 might be a genetic biomarker for susceptibility of lung cancer in Chinese." (PMID 25198518, 2014). "We hypothesized that the single nucleotide polymorphisms (SNPs) of MDC1 which have potencies on affecting MDC1 expression or function were associated with risk of lung cancer." (PMID 25198518, 2014). "Heterozygous NBS1 splicing mutation (IVS11+2insT) detected in sporadic gastric, colorectal and lung cancers led to defects in crucial binding to Mre11, Mdc1 and BRCA1, and caused impaired ATM phosphorylation in response to low-dose irradiation in the heterozygous state." (PMID 24349281, 2013). "Usp28 was initially reported to play an important role in DSB response by stabilizing many proteins, including 53BP1, Chk2, Mdc1, and Nbs1, in H460 lung carcinoma cells." (PMID 34473993, 2021). "Initially, USP28 was reported to play an important role in the DSB response because depletion of USP28 results in the reduction of protein levels of 53BP1, CHK2, MDC1, and NBS1 after ionizing radiation in H460 lung carcinoma cells." (PMID 36436562, 2022). "Aberrant reduction or lack of MDC1 was observed in lung cancer tissues, and down-regulation of MDC1 expression in lung cancer cells would result in defective radiation-induced apoptosis." (PMID 25198518, 2014).
cervical carcinoma (6 papers, 2013 to 2022). A carcinoma arising from either the exocervical squamous epithelium or the endocervical glandular epithelium. "In the present study, we have evaluated the sensitivity to cisplatin in three high risk HPV positive cervical cancer cell lines with respect to the change in MDC1 expression." (PMID 32160908, 2020). "In cervical cancer, USP7 is reported to physically associate with the MRE11-RAD50-NBS1 (MRN)—mediator of DNA damage checkpoint protein 1 (MDC1) complex, enabling DNA repair through the stabilization of MDC1." (PMID 36186590, 2022). "SFN treatment and LATS2 overexpression also inhibited cervical cancer survival after irradiation by suppressing Rad51 and MDC1 nucleus recruitment and DNA damage repair." (PMID 35454780, 2022). "In the present study, we have shown MDC1 can explored as a therapeutic target for improving cervical cancer prognosis in combination with drugs like cisplatin." (PMID 32160908, 2020). "For instance, USP7 has been found to be upregulated in many cervical carcinomas, where its expression positively correlates with that of MDC1, as well as with histological tumor grade." (PMID 32850836, 2020). "Inhibition of USP7 with the compounds GNE-6640 or GNE-6776, however, destabilizes MDC1, as well as sensitizes cervical cancer cells to ionizing radiation-induced genotoxic insult." (PMID 32850836, 2020). "In this regard, we investigated the effect of MDC1 change in expression on the cisplatin sensitivity in cervical cancer cells." (PMID 32160908, 2020). "Our results noticeably indicate that MDC1 knock down increases sensitivity to cisplatin in the cervical cancer cell lines while its overexpression facilitates cisplatin insensitivity in the cells." (PMID 32160908, 2020). "Our results showed high cisplatin sensitivity in combination with MDC1 depletion in all the three cervical cancer cell lines." (PMID 32160908, 2020). "Additionally, SFN treatment and LATS2 overexpression prevented MDC1 and Rad51 from accumulating in the nucleus in cervical cancer cells after being exposed to ionized radiation." (PMID 35454780, 2022). "Our results indicated that SFN could enhance the expression of LATS2 and exert irradiation sensitization in cervical cancer cells by suppressing DNA double-strand break repair, specifically by inhibiting Rad51 and MDC1 nuclear accumulation." (PMID 35454780, 2022). "GIPZ lentiviral MDC1 shRNA (Dharmacon, Inc.)and pCDNA3 MDC1(a kind gift from Prof. Michel Goldberg, Hebrew University, Jerusalem) were used to generate the stable cervical cancer cell lines using Lipofectamine (Thermo fisher scientific)." (PMID 32160908, 2020). "Our studies suggest that MDC1 expression could be a key determinant in cervical cancer prognosis and its depletion in combination with cisplatin has the potential to be explored for the sensitisation of chemo-resistant cervical cancer cells." (PMID 32160908, 2020). "We have shown that MDC1, a master regulator in the ATM-Chk2 pathway can be utilised for the sensitization of cervical cancer cells to chemotherapy." (PMID 32160908, 2020). "In cervical cancer cells, USP7 directly binds to the MRN (MRE11-RAD50-NBS1)-MDC1 (mediator of DNA damage checkpoint protein 1) complex and deubiquitinates and stabilizes MDC1, which results in the maintenance of the DNA damage response (DDR)." (PMID 32300595, 2020). "We found that the recruitment of MDC1 in the nucleus was blocked upon LATS2 overexpression and SFN treatment, resulting in the impaired formation of Rad51 foci under ionizing radiation in cervical cancer cells." (PMID 35454780, 2022). "Since cervical cancer cell lines are HPV positive monitoring E6 and E7 oncogene expression in our modified cell lines would have given greater insight as to increased cisplatin sensitivity in the MDC1 depleted cells." (PMID 32160908, 2020).
cervical carcinoma (continued). "None the less the study clearly signifies that MDC1 in combination with cisplatin can prove to be an effective therapeutic approach for the treatment of cervical cancer patients." (PMID 32160908, 2020).
male infertility (5 papers, 2010 to 2021). The inability of the male to effect fertilization of an ovum after a specified period of unprotected intercourse. "Impaired signaling of DSBs often results in male infertility as observed in H2a.x−/−, Mdc1−/− and Rnf8−/− mice." (PMID 21552324, 2011). "Based on currently available information on MDC1, while we are confident mutations in MDC1 can lead to human male infertility, they are not a high confidence cause of the severe motility disorder seen in this patient." (PMID 34089056, 2021). "Interestingly, unlike MDC1 or H2AX whose deficiency only leads to male infertility, loss of BRIT1 also lead to female infertility with much smaller ovary, suggesting that BRIT1 may also function as a key regulator in oocyte meiotic recombination." (PMID 20107607, 2010).
nasopharyngeal carcinoma (4 papers, 2015 to 2022). A carcinoma arising from the nasopharyngeal epithelium. "Interestingly, elevated MDC1 levels have also been reported in cervical, laryngeal squamous and nasopharyngal carcinomas, which are associated with viral infections and expression of viral proteins, and therefore high levels of DNA damage." (PMID 35624466, 2022).
osteosarcoma (4 papers, 2016 to 2024). A usually aggressive malignant bone-forming mesenchymal neoplasm, predominantly affecting adolescents and young adults. "To this end, we used a human osteosarcoma cell line U2OS stably expressing GFP-tagged MDC1 and RFP-H2B in which the endogenous MDC1 was knocked out using CRISPR/Cas9." (PMID 34650988, 2021). "To test the applicability of the All-in-One Cas9D10A nickase vector system and screening approaches in other cell lines, we targeted the DDR genes MDC1, 53BP1 and RIF1 in human aneuploid osteosarcoma (U2OS) cells and haploid chronic myelogenous leukaemia derived (HAP1) cells." (PMID 27079678, 2016).
ovarian carcinoma (4 papers, 2014 to 2024). A malignant neoplasm originating from the surface ovarian epithelium. "DOCK7 has also been reported to be highly expressed in ovarian cancer, and is recruited into the nucleus by MDC1 to participate in the DNA damage response through the RAC1/CDC42/PAK1 module." (PMID 38385857, 2024). "In clear contrast, dual ATM/ATR inhibition strongly potentiates the activity of both ETs against human cervical and ovarian carcinoma cells by efficiently blocking the formation of γ-H2AX, MDC1, BRCA1 and Rad51 foci following ET-exposure thereby resulting in extensive chromosome damage." (PMID 27029031, 2016).
fibrosarcoma (3 papers, 2017 to 2025). A malignant mesenchymal fibroblastic neoplasm affecting the soft tissue and bone. "At 0.5 hours after 15 Gy, MCA/129 fibrosarcoma specimens accrue about twice as many MDC1 foci as 8 Gy foci, a doubling that is maintained during the 8-hour repair period." (PMID 40402574, 2025). "A similar population, termed mDC1, has recently been identified in murine fibrosarcoma and was significantly reduced in Batf3 knock-out mice, corroborating our findings that CD81+migcDC1s originate from cDC1s." (PMID 37622122, 2023). "The role of STAT3 in DNA damage has been highlighted in fibrosarcoma, where cells with low STAT3 levels have decreased ATM-Chk1 and ATM-Chk2 via transcriptional regulation of MDC1." (PMID 29262529, 2017).
prostate carcinoma (3 papers, 2014 to 2021). A carcinoma that arises from epithelial cells of the prostate gland. "One synonymous variant of MDC1 was reported to be associated with increased radiosensitivity but not prostate cancer risk." (PMID 25198518, 2014).